RIPPLY1 (ripply transcriptional repressor 1)
Description:
Plays a role in somitogenesis. Essential for transcriptional repression of the segmental patterning genes, thus terminating the segmentation program in the presomitic mesoderm, and also required for the maintenance of rostrocaudal polarity in somites (By similarity).
Tractability: No criterion of Open Targets' tractability assessment is met for any kind of drug.
Gene: Protein-coding gene on chromosome X (106,900,063 to 106,903,341, reverse strand). Ensembl gene ENSG00000147223.
Subcellular location: Nucleus
Gene Ontology:
Molecular function: protein binding
Biological process: embryonic pattern specification; negative regulation of DNA-templated transcription; negative regulation of transcription by RNA polymerase II; somite rostral/caudal axis specification; somite specification
Cellular component: nucleus
Homologues: Orthologues: chimpanzee RIPPLY1 (97% identical), macaque RIPPLY1 (95% identical), pig RIPPLY1 (72% identical), rabbit RIPPLY1 (68% identical), rat Ripply1 (64% identical), mouse Ripply1 (61% identical), zebrafish ripply2 (32% identical). Paralogues in human: RIPPLY2 (32% identical), RIPPLY3 (27% identical).
Diseases named in the same sentence as RIPPLY1 in open-access papers:
RIPPLY1 is named in the same sentence as 1 disease in open-access papers, as found by Europe PMC text mining. Sharing a sentence is not in itself a finding about the gene and the disease. The quoted sentences say what the papers report.
spondylocostal dysostosis (1 paper, 2020). Spondylocostal dysplasia is a rare genetic disorder characterized by defects of the bones of the spine (vertebrae) and abnormalities of the ribs. "Although RIPPLY1 has not been associated with a human developmental disease, its paralog, RIPPLY2, causes Spondylocostal Dysostosis (MIM#616566) in an autosomal recessive mode." (PMID 32815649, 2020).